PEAR1 (platelet endothelial aggregation receptor 1)
Diseases named in the same sentence as PEAR1 in open-access papers (continued):
Sharing a sentence is not in itself a finding about the gene and the disease.
limb ischemia (1 paper, 2015). A ischemia that involves the limb. "Interestingly, they also showed that Pear1-/- mice have increased neoangiogenesis compared to wild-type mice using a hind limb ischemia ligation model as well as significantly decreased wound size and closure time in an independent skin wound healing model." (PMID 26406321, 2015).
lung carcinoma (1 paper, 2023). "It is unknown, however, whether PEAR-1 is related to lung cancer risk." (PMID 37848891, 2023).
ovarian carcinoma (1 paper, 2024). A malignant neoplasm originating from the surface ovarian epithelium. "Moreover, the results of online analysis with TIMER2.0 suggested a positive correlation between PEAR1 and CD44 expression levels in numerous cancers, such as blood, brain, colorectal, and ovarian cancer (data not shown)." (PMID 39145451, 2024).
triple-negative breast carcinoma (1 paper, 2024). An invasive breast carcinoma which is negative for expression of estrogen receptor (ER), progesterone receptor (PR), and human epidermal growth factor receptor 2 (HER2). "Levels of PEAR1 protein and PEAR1 phosphorylation at Ser891 were increased in patients with triple-negative breast cancer (TNBC), were positively correlated with expression of LOXL2 and CD44, and were negatively correlated with overall survival." (PMID 39145451, 2024).
cardiovascular disease (8 papers, 2015 to 2024). "SVEP1 and PEAR1 causally and concordantly relate to platelet phenotypes and cardiovascular disease in humans, as determined by Mendelian Randomization." (PMID 36792666, 2023). "In 1938 participants enrolled in the Flemish Study on Environment, Genes and Health Outcomes (51.3% women; mean age 43.6 years), we genotyped 9 tagging SNPs in PEAR1, measured baseline cardiovascular risk factors, and recorded Cardiovascular disease incidence." (PMID 28449647, 2017). "Our results suggest for the first time that genetic variation of PEAR1 is a significant determinant of endothelial function through pathways implicated in cardiovascular disease." (PMID 26406321, 2015). "Consistent with polymorphisms linked to PEAR1 being associated with cardiovascular disease and platelet function, PEAR1-mediated signaling was shown to reinforce and stabilize the interactions between platelets within a forming aggregate." (PMID 25713122, 2015). "Here, the authors identify SVEP1 as a ligand for the orphan receptor PEAR1 and provide insight into the role of this interaction in cardiovascular disease." (PMID 36792666, 2023). "The membrane protein, PEAR1, shows specific expression in endothelial and platelets cells and plays significant roles in platelet activity and cardiovascular disease." (PMID 30721247, 2019). "Similarly, genetically encoded changes in plasma concentrations of both proteins were positively associated with risk of cardiovascular disease (SVEP1 P = 4.5 × 10−12; PEAR1 P = 0.0051)." (PMID 36792666, 2023). "Once understood, PEAR1 may be a novel target for treatment and prevention of cardiovascular disease." (PMID 26406321, 2015). "Therefore, it is important that future investigations aiming to understand the relationship between this gene and cardiovascular disease take into account the pleiotropic nature of PEAR1 in these tissues." (PMID 26406321, 2015). "Our second objective was to further define the impact of PEAR1 on cardiovascular disease computationally through meta-analysis of 75,000 microarrays, yielding insights regarding PEAR1 function, and predictions of phenotypes and diseases affected by PEAR1 dysregulation." (PMID 26406321, 2015). "Based on a predefined hypothesis originating from experimental studies and observations in patients, we could not confirm that PEAR1 is a major susceptibility gene for cardiovascular disease in the population at large." (PMID 28449647, 2017). "Moreover, the Aspirin in Reducing Events in the Elderly trial analyzed the relationship between PEAR1 rs12041331 and cardiovascular outcomes in a healthy elderly population with no previous atherothrombotic cardiovascular disease." (PMID 34135847, 2021).
cancer (4 papers, 2015 to 2024). A tumor composed of atypical neoplastic, often pleomorphic cells that invade other tissues. "Based on our data, future studies should interrogate whether common variants in the PEAR1 region identified by our analysis, are associated with cancer incidence or progression." (PMID 29614055, 2018). "In conclusion, our data suggest that PEAR1 is not only important as gene encoding for a very well-known contact receptor but might also mediate chromosome interactions with genes involved in protein synthesis, cell proliferation and cancer progression through DNA methylation-dependent mechanisms." (PMID 29614055, 2018). "Consequently, we hypothesize that PEAR1 may serve as a more effective therapeutic target in various cancers." (PMID 39145451, 2024). "However, investigations concerning the significance of PEAR1 in cancer remain scarce." (PMID 39145451, 2024). "PEAR1 plays a vital role in TNBC metastasis and serves as a biomarker for cancer prognosis." (PMID 39145451, 2024). "Obvious colocalization of PEAR1 and CD44 was noted on the cancer cell membrane in the TNBC nest." (PMID 39145451, 2024). "PEAR1 interactions with HDGF and PRCC might modulate their cancer-related role and open up for future research of PEAR1 in the tumour biology field." (PMID 29614055, 2018). "However, so far, no reported data have been shown to link PEAR1 to cancer development and progression." (PMID 29614055, 2018).
tumor (4 papers, 2018 to 2025). "Two other chromosome contacts with PEAR1 involve two genes whose abnormal expression is reported to lead to growth of several tumours." (PMID 29614055, 2018). "PEAR1 silencing attenuated lung and liver metastasis but had little effect on tumor growth." (PMID 39145451, 2024). "The platelet endothelial aggregation receptor 1 (PEAR1) gene (Clusters 1 and 2) could be another candidate for a tumor suppressor gene in AML." (PMID 37761935, 2023). "We also revealed that lysyl oxidase–like protein 2 (LOXL2), a well-known regulator of tumor, is an endogenous ligand binding to the PEAR1-EMI domain and facilitating PEAR1 Ser891 phosphorylation, which is essential for the binding of PEAR1 to CD44." (PMID 39145451, 2024).
infection (1 paper, 2024). The state of being infected such as from the introduction of a foreign agent such as serum, vaccine, antigenic substance or organism. "In future studies, we will conduct experiments in mice, such as gene knockout or adeno-associated virus (AAV) infection experiments, to further explore the role of PEAR1 in skeletal muscle post-injury regeneration and the molecular mechanism of PEAR1 in Notch signaling pathway." (PMID 39765730, 2024).
respiratory diseases (1 paper, 2022). "Here we show that the intratracheal nebulization of monoclonal antibodies targeting PEAR1 significantly ameliorates the degree of PF, indicating that the inhalation of antibodies may serve as an efficient strategy for the treatment of respiratory diseases." (PMID 36402779, 2022).
PEAR1 also shares sentences with these, for which no sentence is quoted: ischemic stroke (4 papers); diabetes (2); high blood pressure (2); acute coronary syndrome (1); acute myocardial infarction (1); atrial fibrillation (1); colorectal (1); dementia (1); hemorrhagic stroke (1); hyperlipoproteinemia (1); Hypertension (1); intracranial hemorrhage (1); melanoma (1); membranous nephropathy (1); Miscarriage (1); non-small cell lung carcinoma (1); osteoarthritis (1); pancreatic cancer (1); Peptic ulcer (1); preeclampsia (1); prostate carcinoma (1); venous thromboembolism (1).